TET2 (tet methylcytosine dioxygenase 2)
Diseases named in the same sentence as TET2 in open-access papers (continued):
Sharing a sentence is not in itself a finding about the gene and the disease.
myeloid malignancies (continued). "In this review, we will discuss the current understanding of pre-leukemic biology in myeloid malignancies, and how mutations in two key epigenetic regulators, DNMT3A and TET2, may contribute to disease pathogenesis." (PMID 27597933, 2016). "Other molecular mechanisms, including mutations of additional genes and/or epigenetic regulation may affect TET2 expression in myeloid neoplasms." (PMID 26984174, 2016). "TET2 is the most frequently mutated gene in our patient cohort and is known to be frequently mutated in elderly persons without myeloid neoplasms." (PMID 27029036, 2016). "Taken together, our findings suggest that decreased TET2 expression is observed in myeloid neoplasms and does not correlate with TET2 mutation status." (PMID 26984174, 2016). "If so, then we speculate that this action may be important for the role of TET2 in ES cell pluripotency and myeloid tumour suppression." (PMID 25276435, 2014). "Around 60% of CD34+ cells from patient 2 [P2(h)] exhibited a heterozygous JAK2V617F mutation (JAK2V617F/WT) whereas no mutation was identified in these cells in ASXL1 and the other genes involved in myeloid malignancies, including TET2, EZH2, DNMT3A, IDH1 and SRSF2." (PMID 24066127, 2013). "While responses to hypomethylating agents (HMAs) in IDH and TET2 mutated myeloid neoplasms did not result in much better responses than in unselected MDS/AML patients, the development of selective inhibitors of mutated IDH1 and IDH2 is a success story of targeted therapy in these MDS/AML genotypes." (PMID 40374809, 2025). "This study found that mice with non-catalytic TET2 mainly developed myeloid malignancies, while mice with complete loss of TET2 developed both myeloid and lymphoid disorders, supporting the unique non-catalytic role of TET2 in the hematopoietic stem and progenitor cell homeostasis." (PMID 37563110, 2023). "Therefore, we can speculate that DMOG can regulate TET2 and affect the occurrence and development of myeloid malignancies by controlling the expression of AIM2i-RGs." (PMID 36248785, 2022). "The two TET2 mutations were likely pathogenic as we identified a nonsense allele (TET2 p.Q1702*), which we validated by PCR and sequencing, and a mutation in a highly conserved residue in TET2 commonly mutated in myeloid malignancies (TET2 p.E1874K)." (PMID 28721364, 2015). "Therefore, it is likely that TET2 plays an important role in regulation of hematopoietic differentiation and may even serve as a prognostic tool in myeloid malignancies." (PMID 25276435, 2014). "However, the specific content of 5 hmC and 5 mC in genes hypermethylated in patients with myeloid malignancies, especially in patients in whom the gene TET2 is mutated, has not been analyzed." (PMID 22328940, 2012). "Due to the role of TET2 in promoting DNA stability, PARPis represent a class of drugs that offer potential effectiveness in treating HMA-resistant myeloid neoplasms." (PMID 31001476, 2019).
myeloid malignancies (continued). "Ten-Eleven Translocation 2 (TET2) gene is located at chromosome 4q24, a region wherein recurrent microdeletions, translocations, and uniparental disomy occurred frequently in patients with myeloid malignancies." (PMID 36611455, 2023). "The effect of Epag on TET2 mutant myeloid neoplasm patient-derived mononuclear cells was tested in 9 patients (5 with biallelic and 4 with monoallelic inactivation of TET2) using colony-forming assays in the presence or absence of Epag." (PMID 35085104, 2022). "Myeloid Malignancy-Related Gene Mutation Screening: A panel of 67 genes associated with the diagnosis, treatment, prognosis, and recurrence of myeloid malignancies (including KIT, SRSF2, TET2, and ASXL2) was analyzed, with no relevant mutations identified." (PMID 40071101, 2025). "For example, microhomology-mediated recurrent deletions of CALR, ASXL1, and SRSF2 and non-recurrent deletions in TET2, DNMT3a, CEBPA, and RUNX1 have been reported in myeloid neoplasms." (PMID 36011278, 2022).
myelodysplastic syndrome (155 papers, 2010 to 2026). A clonal hematopoietic disorder characterized by dysplasia and ineffective hematopoiesis in one or more of the hematopoietic cell lines. "Loss-of-function heterozygous mutations in TET2 (tet methylcytosine dioxygenase 2) are among the most prevalent and significant drivers of CH and myelodysplastic syndromes, an age-related hematological disease." (PMID 40230417, 2025). "Previous studies in 2009 have shown TET2 mutation to be a favorable independent prognostic factor in myelodysplastic syndrome (MDS), and TET2 mutations were associated with poor outcomes in CMML patients." (PMID 40013211, 2025). "Recently, a study showed that the activation of the cGAS/STING/NLRP3 axis by cytoplasmic DNA in Tet2-deficient hematopoietic stem/progenitor cell line promotes myelodysplastic neoplasms development." (PMID 37816954, 2023). "Bcor loss also showed myeloid-biased hematopoiesis and promoted the initiation and progression of myelodysplastic syndrome in collaboration with Tet2 loss." (PMID 37266576, 2023). "Myelodysplastic syndromes are characterised by clonal haematopoiesis, with the affected cells often harbouring mutations in the TET2 gene, an important regulator of DNA methylation state." (PMID 36737440, 2023). "TET2 is frequently mutated in human chronic myelomonocytic leukemia, and its loss promotes myelodysplastic syndrome (MDS) and myeloid and lymphoid leukemia in mice." (PMID 35235365, 2022). "Studies in human TET proteases have shown that mutations in TET2 are most relevant to developing hematological malignancies and are also associated with increased risks of autoimmunity in myelodysplastic syndrome patients." (PMID 36553013, 2022). "In hematologic tumors such as acute myeloid leukemia and myelodysplastic syndromes, loss-of-function mutations in TET2 are known to occur frequently, resulting in decreased and hypermethylated 5hmC." (PMID 36203466, 2022). "SRSF2/TET2 are commonly co-mutated in myelodysplastic syndromes (MDS) characterized by myelodysplasia and monocytosis." (PMID 33436578, 2021). "Although somatic alterations of TET2 have been found in several cancers, these mutations are majorly associated with myelodysplastic syndromes." (PMID 33477877, 2021). "Tet methylcytosine dioxygenase 2 (TET2) is one of the most frequently mutated genes in myelodysplastic syndrome (MDS)." (PMID 34449560, 2021). "Somatic loss of function mutations in TET2 are frequently observed in myelodysplastic syndromes (MDS), myeloproliferative neoplasms (MPN), and AML." (PMID 28533480, 2017). "Other groups have since reported a similar prevalence of TET2 mutations in myelodysplastic syndromes and other myeloid diseases." (PMID 21811504, 2012). "Studies in humans have shown that mutations in TET2 are thought to be the most relevant of the various TETs in developing hematological malignancies and are also associated with increased risks of autoimmunity in myelodysplastic syndrome patients." (PMID 36553013, 2022). "In support of a role of TET2 in the regulation of inflammatory reactions in human cells, TET2 mutations in human macrophages prepared from bone marrow of patients with myelodysplastic syndromes were associated with increased induction of IL6 upon LPS stimulation." (PMID 35011643, 2021). "TET2 mutations frequently occur in myelodysplastic syndromes and myeloid cancers." (PMID 33114351, 2020). "However, TET2 mutations have been shown to predict the response of patients with myelodysplastic syndrome to hypomethylating agents." (PMID 28039446, 2017). "In addition to PTMs, mutations within the spacer region of Tet2 were observed in myelodysplastic syndrome (MDS), thus further highlighting the importance of this region." (PMID 27446199, 2016). "Additionally, whether the TET2-dependent mechanisms we present here occurs in patients with TET2 mutations, such as those with myelodysplastic syndromes or clonal hematopoiesis, remain unknown." (PMID 38225226, 2024).
myelodysplastic syndrome (continued). "Some studies have reported an association between TET2 mutation and favorable outcome of myelodysplastic syndrome (MDS) following treatment with hypomethylating chemotherapy, such as 5′-Aza, though other studies have not replicated these findings." (PMID 36480300, 2023). "TET2 is among the most commonly mutated genes in adult myeloid malignancies, occurring in ~25% and ~50% of cases of myelodysplastic syndromes (MDS) and chronic myelomonocytic leukemia (CMML), respectively." (PMID 33921666, 2021). "TET2 mutations are frequently acquired during the progression of myeloproliferative neoplasms (MPN) or myelodysplastic syndromes (MDS) to AML6." (PMID 32066746, 2020). "However, TET2 was reported to play a regulatory role in myeloproliferative neoplasms and myelodysplastic syndromes in the form of functional deletion mutations, whereas TET1 and TET3 were rarely characterized of functional deletion mutations to function in hematological tumors." (PMID 32014008, 2020). "More importantly, TET genes, especially TET2 are frequently mutated in various cancers, including myelodysplastic syndrome (MDS), cohort of chronic myelomonocytic leukemia (CMML), primary and secondary AML, blastic plasmacytoid dendritic neoplasm." (PMID 28488246, 2017). "TET2 somatic mutations occur in 7–23% of AMLs and 25% of myelodysplastic syndromes (MDS), and are distributed across the entire coding sequence without clustering into obvious hot spots." (PMID 26284582, 2016). "In contrast, the TET2, FLT3, RUNX1, BCOR and spliceosome mutations were more common in the IDO1-high group, which were commonly enriched in myelodysplastic syndrome (MDS)-transformed AML." (PMID 40234305, 2025). "Mutations in tet methylcytosine dioxygenase 2 (TET2) and DNA methyltransferase 3 alpha (DNMT3A) in AML and myelodysplastic syndrome lead to either hypermethylation or hypomethylation of enhancers, thereby affecting the accessibility of specific TFBS." (PMID 40032852, 2025). "In myelodysplastic syndromes (MDS), TET2-mutated clones frequently coexist with NK cells harboring the same mutation." (PMID 41280924, 2025). "As a positive control for increased serial plating, we used RNP that disrupts the endogenous TET2 locus in HSPCs as it has been previously demonstrated that these cells exhibit key features of preleukemia/clonal hematopoiesis." (PMID 38169468, 2024). "It is further theorized that hypomethylating agents such as 5-azacytidine would be effective in TET2-mutated cancers given the significantly increased efficacy of 5-azacytidine in TET2 mutant subgroups in the treatment of myelodysplastic syndrome." (PMID 36776886, 2023). "The ten-eleven translocation 2 gene tet2, a dioxygenase enzyme that can catalyze the conversion of 5-methylcytosine (5mC) to 5-hydroxymethylcytosine, is a recurrently mutated gene in hematological malignancies, including myelodysplastic syndrome (MDS)." (PMID 37937078, 2023). "The Tet methylcytosine dioxygenase 2 (TET2) is generally believed to be involved in the occurrence of hemopathy like myelodysplastic syndrome (MDS) or AML." (PMID 36595106, 2023).
myelodysplastic syndrome (continued). "CMML is characterized by sustained monocytosis and an overlap of myeloproliferative neoplasms (MPN) and myelodysplastic syndromes (MDS) resulting from a cumulative mutational landscape including TET2 (60%), SRSF2 (50%), ASXL1 (40%), and the oncogenic RAS pathway (30%) mutations." (PMID 35884612, 2022). "SRT1720 has also been shown to enhance TET2 enzymatic activity in myelodysplastic syndrome hematopoietic stem/progenitor cells." (PMID 35351824, 2022). "Tet2 knockout mice are viable but develop myelodysplastic syndrome (MDS) and CMML-like disease by one year of age." (PMID 35150568, 2022). "In myelodysplastic syndromes (MDS) and AML, TET2 mutations are present in 20%–30% of cases, ranging up to 50% in patients affected by chronic myelomonocytic leukemia (CMML)." (PMID 33808599, 2021). "Driver mutations, such as DNMT3A, TET2, and ASXL1, appear early in AML clones and in the myelodysplastic syndrome (MDS)." (PMID 33363031, 2020). "The authors found that SIRT1 levels, and hence TET2 activity, were decreased in aberrant HSPCs in myelodysplastic syndrome (MDS), whereas overexpression of SIRT1 or its activation by agonist SRT1720 resulted in reduced myelodysplastic HSC survival." (PMID 33114351, 2020). "In Itzykson’s study, azacitidine conferred a better response rate on patients with myelodysplastic syndromes and low blast count AML, which showed TET2 mutations’ predictive value of response to hypomethylated agents." (PMID 31023266, 2019). "A model of myelodysplastic syndrome (MDS) where zebrafish tet2 (ten-eleven translocation methylcytosine dioxygenase 2) was disrupted, mimics a frequently observed loss-of-function mutation found in humans." (PMID 31731811, 2019). "In myelodysplastic syndromes and in clonal hematopoiesis (CHIP), EZH2 and TET2 have been reported to be associated with higher rate of cardio-vascular events, and TET2 mutations (at low allelic burden) seem to positively predict the response to azacitidine." (PMID 30574454, 2018). "24-month-old Tet2 mutant zebrafish display a myelodysplastic syndrome that is also observed in human patients and mouse models with TET2 mutation in their haematopoietic cells." (PMID 29616219, 2018). "TET2 mutations occur in around 50% of chronic myelomonocytic leukemia (CMML), a subtype of myelodysplastic syndrome/myeloid proliferative neoplasm (MDS/MPN), as well as in around 30% of myeloproliferative neoplasms and AML." (PMID 28471392, 2017). "Mutations in TET2 may be an early phenomenon as they are found in approximately 20% of preleukaemic conditions such as MDS (myelodysplastic syndrome) and MPN (myeloproliferative neoplasms)." (PMID 28286768, 2017). "Interestingly, TET2 mutations have recently been proposed as a predictive biomarker of responsiveness to hypomethylating agents in myelodysplastic syndrome (MDS) and low blast count AML." (PMID 25932335, 2015). "Loss of heterozygosity affecting these two chromosomes and mutations in TET2 and EZH2 are indicative of a myelodysplastic syndrome with a poor prognosis." (PMID 25177364, 2014). "Genes that regulate DNA methylation and demethylation (e.g., DNMT3A, IDH1 and IDH2, TET2) are commonly mutated in adult AML and myelodysplastic syndromes (MDS), although the frequency of these mutations appears much lower in pediatric AML." (PMID 24672775, 2014). "Among hematological malignancies, TET2 is mutated most frequently in AML, secondary AML (sAML), myelodysplastic syndrome (MDS), systemic mastocytosis, chronic myelomonocytic leukemia (CMML), and other MPNs." (PMID 24202321, 2013). "Of the 6 individuals with copy losses in the TET2 gene region, 2 of these individuals had an incident hematologic cancer diagnosis (1 myelodysplastic syndrome & 1 multiple myeloma)." (PMID 23533652, 2013).